TSC1 (TSC complex subunit 1)
Diseases named in the same sentence as TSC1 in open-access papers (continued):
Sharing a sentence is not in itself a finding about the gene and the disease.
pulmonary fibrosis (4 papers, 2015 to 2024). Chronic progressive interstitial lung disorder characterized by the replacement of the lung tissue by connective tissue, leading to progressive dyspnea, respiratory failure, or right heart failure. "Our previous work demonstrated that Tsc1 was a direct target of miR-301a and was involved in pulmonary fibrosis." (PMID 35211358, 2022). "Our previous study demonstrated that ablation of miR-301a in mice protected against bleomycin-induced lung fibrosis through the Tsc1/mTOR axis signaling pathway." (PMID 35211358, 2022). "Our previous study reported that deletion of miR-301a protected mice from bleomycin-induced lung fibrosis by reducing mTOR activation in a Tsc1-dependent manner." (PMID 35211358, 2022). "It found that the deletion of miR-301a alleviated pulmonary fibrosis by targeting TSC1, which negatively regulated its downstream mTOR pathway." (PMID 32585629, 2020). "The present study next confirmed that inhibiting the expression of TSC1 in miR-301a−/− mice significantly activated mTOR and promoted pulmonary fibrosis." (PMID 32585629, 2020). "The findings also revealed a significant role for the miR-301a/TSC1/mTOR axis in pulmonary fibrosis." (PMID 32585629, 2020). "The results demonstrated that the miR-301a/TSC1/mTOR axis was a key positive regulator of fibrogenesis, providing a new target for the clinical treatment of pulmonary fibrosis." (PMID 32585629, 2020). "Collectively, the results suggested that miR-301a activated the mTOR pathway by negatively regulating TSC1 in fibroblasts and promoted the progression of pulmonary fibrosis." (PMID 32585629, 2020). "Cell proliferation in fibrotic lung tissues was measured to evaluate the role of miR-301a and TSC1 in regulating lung fibrosis." (PMID 32585629, 2020). "The findings revealed the crucial role of the miR-301a/TSC1/mTOR axis in the pathogenesis of pulmonary fibrosis, suggesting that miR-301a might serve as a potential therapeutic target." (PMID 32585629, 2020). "Furthermore, this study demonstrated that TSC1 was a functional target of miR-301a in fibroblasts, and the negative regulation of TSC1 by miR-301a promoted the severity of pulmonary fibrosis through the mammalian target of rapamycin (mTOR) signaling pathway." (PMID 32585629, 2020). "To investigate the role of mTOR signaling in AECs during the process of pulmonary fibrosis, we obtained transgenic SPC-rtTA/TetO-Cre/TSC1+/f (STT) mice by crossing three types of transgenic mice, SPC-rtTA, TetO-Cre and TSC1f/f, with each other." (PMID 26382847, 2015).
sarcoma (4 papers, 2016 to 2025). A usually aggressive malignant neoplasm of the soft tissue or bone. "While FISH analysis was performed in only six patients in this study, expanding molecular profiling in future research may identify actionable targets, such as NTRK fusions or TSC1/2 mutations, which are increasingly relevant in sarcoma treatment." (PMID 40894946, 2025).
tumor syndrome (4 papers, 2015 to 2017). "TSC1 and TSC2 are the tumor-suppressor genes mutated in tumor syndrome TSC (tuberous sclerosis complex)." (PMID 27409169, 2016).
adenoma (3 papers, 2012 to 2022). A neoplasm arising from the epithelium. "All cystic and adenoma-like regions stained strongly for phosphorylation of ribosomal protein S6 (Ser240/244), indicative of Tsc1 deletion." (PMID 29133867, 2017). "We have shown that defective LKB1/TSC1/TSC2/mTORC1 signaling in mesenchymal cells is sufficient to cause epithelial hyperplasia, adenoma and paratubal cysts in oviducts, and uterine endometrial cancer in mice." (PMID 22916036, 2012). "TSC1 and TSC2 are growth suppressor genes, therefore, we conclude that loss of TSC2 could contribute to adenoma development." (PMID 35887000, 2022). "As reported, within 2 months of homozygous deletion of Tsc1 in 6–8 week old mice, kidneys developed a severe polycystic phenotype with intermixed regions of adenoma-like epithelial proliferation but did not develop renal AMLs." (PMID 29133867, 2017).
allergic asthma (3 papers, 2017 to 2025). A asthma with a basis in a pathological type I hypersensitivity reaction. "A recent study using mice with myeloid-specific deletion of TSC1 found that TSC1-deficient mice are highly resistant to M2-polarized allergic asthma, and identified a key role for TSC1 in orchestrating macrophage polarization via mTOR-dependent and independent pathways." (PMID 28225024, 2017). "This structural basis underpins IGF2BP2′s ability to recognize m6A-modified transcripts such as TSC1, allowing it to stabilize TSC1 mRNA and modulate macrophage polarization, thus linking RNA structural specificity to immune function in allergic asthma." (PMID 41008562, 2025).
anaplastic thyroid cancer (3 papers, 2016 to 2026). "A cBioPortal query (2285 cases) found TSC1 alterations in 2% and TSC2 in 1%, mostly deletions, enriched in poorly differentiated and anaplastic thyroid carcinomas." (PMID 41518426, 2026).
angiosarcoma (3 papers, 2016 to 2017). A malignant tumor arising from the endothelial cells of the blood vessels. "In support of the pro-angiogenic phenotype we observe in our model, it was recently reported that an endothelial-cell-specific deletion of Tsc1 in a mouse model of angiosarcoma led to retinal angiogenesis and formation of vascular tumors." (PMID 27655340, 2016).
diabetes (3 papers, 2015 to 2023). "Diabetes markedly increased fibrogenesis; it is plausible that under the pro-fibrogenic conditions of diabetes, the beneficial hemodynamic effects of Tsc1 KO resulted in partial improvement of kidney function." (PMID 32726619, 2020). "Moreover, Tsc1 deletion in RPTCs of Akita mice was associated with decreased glomerular size, probably because of enhanced sodium delivery to the distal part of the nephron, but still was ineffective in preventing the decline of renal function in diabetes by treatment with SGLT2i." (PMID 32726619, 2020). "Moreover, Tsc1 deletion in RPTCs of diabetic animals prevented the inhibition of mTORC1 by dapagliflozin; this abolished the renal-protective effects of SGLT2i in diabetes." (PMID 32726619, 2020).
Down syndrome (3 papers, 2018 to 2025). "In this study, we focused on syndromic disorders caused by seven tumor suppressor genes: FH, NF1, PTCH1, RB1, STK11, and TSC1/2." (PMID 40702147, 2025).
ganglioglioma (3 papers, 2018 to 2023). A well differentiated, slow growing neuroepithelial neoplasm composed of neoplastic, mature ganglion cells and neoplastic glial cells. "In patients F43 with FCD type IIB and F70 with ganglioglioma, DEPDC5 and TSC1 were deleted, respectively, together with many other genes through somatic chromosomal deletions." (PMID 36864519, 2023).
Hepatitis (3 papers, 2021 to 2024). Inflammation of the liver. "To clarify the mechanisms of action of mTORC1-activated KCs in hepatitis, we analyzed the differentially expressed genes related to the complement system in Tsc1-/- KCs." (PMID 36494334, 2022). "To evaluate the role of hepatocyte mTORC1 activation in KC maintenance and hepatitis, we generated a mouse model with hepatocyte-specific Tsc1 ablation (Alb-Tsc1-/- mice)." (PMID 36494334, 2022). "By using hepatocyte-specific or macrophage-specific Tsc1-knockout mice, we found that mTORC1-activated hepatocytes protect the liver from Con-A-induced hepatitis by killing the surrounding KCs, whereas mTORC1-activated KCs aggravate liver injury by stimulating the complement alternative system." (PMID 36494334, 2022). "In addition, and as previously reported, the marker of hepatocellular damage ALT as well as several other markers of liver damage detected by anatomopathological analysis (necrosis, fibrosis, and hepatitis) (bottom) were increased in Li-TSC1−/− mice and mainly absent in Li-RagAGTP/Δ mice." (PMID 34135321, 2021).
hypertrophic cardiomyopathy (3 papers, 2014 to 2023). A condition in which the myocardium is hypertrophied without an obvious cause. "Importantly, miR-451 regulates autophagy in cardiomyocytes by targeting TSC1 and is decreased in hypertrophic cardiomyopathy showing a negative correlation with left ventricular mass." (PMID 29937989, 2018).
lung disease (3 papers, 2010 to 2022). "Sporadic LAM is a progressive pulmonary disorder that is genetically related to TSC in that somatic mutations in the TSC1 or TSC2 genes have been identified in abnormal lung tissues from LAM patients." (PMID 20146790, 2010).
lymphangiosarcoma (3 papers, 2017 to 2023). A malignant neoplasm arising from the endothelial cells of the lymphatic vessels. "We recently created a new mouse model for human lymphangiosarcoma by deleting Tsc1 in endothelial cells and consequent hyper-activation of mTORC1." (PMID 32336756, 2020). "By using an inducible Tie2-cre to disrupt Tsc1 in postnatal mice, cutaneous lymphangiosarcomas and Prox1-positive thin-walled vascular channels developed with an increase in VEGFA levels within cutaneous tumors." (PMID 28695825, 2017).
multiple myeloma (3 papers, 2015 to 2021). "Previous reports show that changes in TSC1 or miR-130a expression is associated with the modulation of one or more of the cellular properties like proliferation, apoptosis, colony forming ability and invasion in several cancers such as prostate, multiple myeloma, gastric, SACC, and ovarian cancer." (PMID 33833339, 2021). "OIP5-AS1 repressed multiple myeloma progression by regulating miR-27a-3p/TSC1 axis." (PMID 32410883, 2020). "Thus, miR-451 targets TSC1 to mediate PI3K/Akt/mTOR signaling, which plays an essential role in myeloma stem cell biology." (PMID 25915427, 2015).
oncocytic tumor (3 papers, 2021 to 2022). "TSC1 and TSC2 mutations occur in sporadic high-grade oncocytic tumor (HOT) of the kidney and eosinophilic vacuolated tumor (EVT) of the kidney." (PMID 34680979, 2021).
oral cancer (3 papers, 2012 to 2021). "MAPKAP1, TSC1 and RPTOR are also involved in mTOR signaling, which has been associated with tumor growth and immune regulation in the local microenvironment of oral cancers." (PMID 30308005, 2018).
osteosclerosis (3 papers, 2017 to 2023). Abnormally high bone density. "Eliminating TSC1 (tuberous sclerosis 1), a mTORC1 inhibitor, to constitutively activate mTORC1 in pre-osteoblasts stimulated osteosclerosis and CXCL12 secretion, thus exacerbating OA." (PMID 36737426, 2023). "We found that osteocyte TSC1 disruption reduced sclerostin in bone, leading to osteosclerosis with enhanced bone formation in mice." (PMID 31088250, 2019). "Although osteocyte TSC1 disruption increased RANKL expression and osteoclast formation, it markedly reduced sclerostin production in bone, resulting in severe osteosclerosis with enhanced bone formation in mice." (PMID 31088250, 2019). "Our recent study showed that although overactivation of mTORC1 in preosteoblasts through TSC-1 KO resulted in osteosclerosis and skeletal dysplasia in mice, no significant spinal deformity was present." (PMID 28523278, 2017).
ovarian carcinoma (3 papers, 2003 to 2024). A malignant neoplasm originating from the surface ovarian epithelium. "have shown that the overexpression of miR-130a in ovarian cancer cells significantly reduced the expression of TSC1 at the protein level." (PMID 33833339, 2021). "The distal locus on 9q includes two genes with potential roles as tumour suppressor genes in ovarian cancer; the TSC1 gene at 9q34 and the DBCCR1 gene at 9q32–33." (PMID 12771925, 2003).
psoriasis (3 papers, 2022 to 2025). An autoimmune condition characterized by red, well-delineated plaques with silvery scales that are usually on the extensor surfaces and scalp. "Ablation of TSC1 in mice disrupts TJs and causes a psoriasis-like phenotype." (PMID 36139422, 2022). "Concerning miRNAs, it has been identified that hsa-miR-19a-3p has great potential to become a biomarker for psoriasis because it binds to the mRNA of seven genes (CAST, TSC1, SPATA2, ERAP1, TNIP1, ERBB3 and SDC4) thatare associated with psoriasis." (PMID 40725409, 2025). "Junctional TSC1 levels in epithelial tissues are markedly reduced in Crohn’s disease or psoriasis patients, together with the tight junction structure impairment, implying that TSC1 deficiency may also be involved in tight junction-related diseases." (PMID 40655946, 2025).
urothelial carcinoma (3 papers, 2017 to 2024). A malignant neoplasm derived from the transitional epithelium of the urinary tract (urinary bladder, ureter, urethra, or renal pelvis). "Combined FIGHT-201 (n = 149) and FIGHT-207 (n = 13) data for patients with urothelial carcinoma identified TSC1, which was reported in earlier analysis and CDKN1A, which was now found to be correlated nominally significantly with objective response." (PMID 38710951, 2024).
Abdominal obesity (2 papers, 2019 to 2024). Excessive fat around the stomach and abdomen. "Acupuncture can reduce abdominal obesity and shield against metabolic diseases through regulating gut flora, or through its control of hypothalamus’ autophagy and its impact on TSC1-mTOR." (PMID 39138739, 2024).
acute myeloid leukemia (2 papers, 2022 to 2025). Acute myeloid leukemia (AML) is a group of neoplasms arising from precursor cells committed to the myeloid cell-line differentiation. "In a study on acute myeloid leukemia (AML) cells, the results of genome-wide CRISPR/Cas9 screens revealed negative regulators of the MAPK and mTORC1 signaling pathways, including LZTR1, NF1, and TSC1 or TSC2, were associated with sorafenib resistance." (PMID 35715750, 2022).
Arrhythmia (2 papers, 2020 to 2023). Any cardiac rhythm other than the normal sinus rhythm. "Dysregulation of protein products of CALM1 and TSC1 has been associated with arrhythmia and might be relevant in the arrhythmogenesis processes of CHCM." (PMID 38173812, 2023). "Intriguingly, flies with cardiac-specific knockdown of Tsc1 showed no age-dependent increases in heart period, diastolic intervals, and arrhythmia." (PMID 31884871, 2020).
arterial hypertension (2 papers, 2021 to 2025). "Secondly, the study population was small and heterogeneous in terms of age, presence of arterial hypertension, the extent of renal involvement, genetic background (TSC1, TSC2, TSC2+PKD1), and treatment with mTOR inhibitors." (PMID 34912759, 2021). "According to another hypothesis, haploinsufficiency of TSC1/TSC2 genes causing mTOR pathway overactivity may lead to glomerular hypertrophy and hyperfiltration; however, the mechanisms linking glomerular hyperfiltration to hypertension in TSC are not well understood." (PMID 41227201, 2025).
brain ischemia (2 papers, 2017 to 2025). Diminished or absent blood supply to the brain caused by obstruction (thrombosis or embolism) of an artery resulting in neurologic damage. "Particularly, in vitro downregulation of TSC-1 induces a blockade of the autophagy flux that is prevented by the genetic overexpression of TSC-1, which enhances neuronal survival through the restoration of the autophagic flux, suggesting a neuroprotective role for autophagy in brain ischemia." (PMID 28282924, 2017).
cystadenoma (2 papers, 2012 to 2020). A benign or borderline cystic epithelial neoplasm arising from the glandular epithelium. "Kidneys from Tsc1∆/∆ mice also exhibited multiple cystadenomas and increased immunostaining of phosphorylated ribosomal protein S6 (pS6) compared to Tsc1+/+ mice, consistent with constitutive mTOR activation following Tsc1 deletion." (PMID 32927859, 2020).
developmental and epileptic encephalopathy (2 papers, 2024 to 2025). An epilepsy associated with developmental impairment that may be due to either the underlying etiology or the superimposed epileptic activity, or both. "Two TSC1 de novo variants, including c.1498 C > T/p.Arg500* and c.2356 C > T/p.Arg786*, were identified in two patients with developmental and epileptic encephalopathy (DEE)." (PMID 40217423, 2024).
dilated cardiomyopathy (2 papers, 2016 to 2025). Cardiomyopathy which is characterized by dilation and contractile dysfunction of the left and right ventricles. "It has been reported that cardiac-specific TSC1-deficient mice, which were generated by crossing floxed TSC1 mice with myosin light chain 2v-promotor driven Cre recombinase knock-in mice, had a median survival of 6 months and developed dilated cardiomyopathy." (PMID 27023784, 2016).
dysplasia (2 papers, 2019 to 2020). A usually neoplastic transformation of the cell, associated with altered architectural tissue patterns. "Interestingly, the extent of spinal dysplasia was severe in Prrx1-TSC1 null mice but relatively slight in BGLAP-TSC1 null mice, suggesting that TSC1 gene plays different roles in diversiform osteoblast precursors for mammalian endochondral ossification." (PMID 32309432, 2020).
gastric adenocarcinoma (2 papers, 2019 to 2025). "As reported, inhibition of PI3K/AKT signaling pathway could reversed multidrug resistance through TSC1/2 complex and Rheb in human gastric adenocarcinoma cells." (PMID 31582906, 2019).
gastrointestinal stromal tumor (2 papers, 2016 to 2021). "The characterization of recurrent mutations of cKIT in gastrointestinal stromal tumors (GIST) and TSC1/2 in malignant peripheral epithelioid cell tumors (PEComa) formed the basis for the respective repurposing of imatinib and sirolimus." (PMID 27211532, 2016).
glioblastoma (2 papers, 2019 to 2020). The most malignant astrocytic tumor (WHO grade IV).
Glucose intolerance (2 papers, 2011 to 2021). Glucose intolerance (GI) can be defined as dysglycemia that comprises both prediabetes and diabetes. "Other models of Akt suppression in the liver (i.e., deletion of hepatic insulin receptor or Akt2) also result in a reduction in TG accumulation along with glucose intolerance similar to that of the Tsc1−/− mice." (PMID 21479224, 2011). "Following systemic administration of glucose, both male and female Tsc1−/− mice exhibited mild but significant glucose intolerance compared to Tsc1+/+ mice." (PMID 21479224, 2011). "These trends suggest that glucose intolerance worsened with HFD + rapamycin in both Tsc1+/+ and Tsc1−/− mice without significant differences between the two genotypes." (PMID 21479224, 2011).
hemangioma (2 papers, 2007 to 2022). A benign vascular lesion characterized by the formation of capillary-sized or cavernous vascular channels. "In particular, tsc1+/- or tsc2+/- mutant mice which are characterized by high level of mTOR-mediated phosphorylation of Eif4ebp1 and Rps6kb1, have hemangiomas with poorly developed vasculature that are prone to rupture." (PMID 17892597, 2007).
Hepatic steatosis (2 papers, 2021 to 2025). Steatosis is a term used to denote lipid accumulation within hepatocytes. "However, studies of genetically engineered mice with liver-specific knockout of Tsc1 have demonstrated that activation of mTORC1 in hepatocytes surprisingly protects against diet-induced hepatic steatosis." (PMID 34267188, 2021). "Surprisingly, activating mTORC1 through liver-specific deletion of Tsc1 does not induce fat accumulation in the liver and even protects the liver against high-fat diet (HFD)-induced hepatic steatosis." (PMID 34267188, 2021).
Hydrocephalus (2 papers, 2013 to 2016). Hydrocephalus is an active distension of the ventricular system of the brain resulting from inadequate passage of CSF from its point of production within the cerebral ventricles to its point of absorption into the systemic circulation. "The causes of ventricular dilation and hydrocephalus were not identified in the Tsc1-KOs, although cryptic nodules obstructing CSF flow or disrupting the ependymal lining are possible causes." (PMID 27693047, 2016).